CRP (C-reactive protein)
Diseases named in the same sentence as CRP in open-access papers (continued):
Sharing a sentence is not in itself a finding about the gene and the disease.
heart failure (continued). "Other significant risk factors were complications such as lung embolisation, renal insufficiency and heart failure, or a higher c-reactive protein level at admission (p = 0.021, p < 0.001, p < 0.001, p = 0.006, respectively)." (PMID 37107067, 2023). "Cardiovascular mortality was correlated to heart failure, shock on admission, and C-reactive protein levels." (PMID 36811731, 2023). "This study found that increasing doses of Canakinumab resulted in less hospitalizations for heart failure and heart failure-related mortalities in patients with prior MI and high CRP levels." (PMID 36816471, 2023). "Further multivariate logistic regression analysis revealed that CRP level >5 mg/L was an independent predictor of early postoperative cardiac insufficiency, and NLR >3.5 was an independent predictor of death within 30 days after surgery." (PMID 37063874, 2023). "Multivariate analysis revealed heart failure with reduced EF (HFrEF), shock on admission, and CRP levels to be predictors of in-hospital mortality." (PMID 36811731, 2023). "The vaccinated group had lower levels of severity and CRP, a higher medical history of heart failure or malignancy, and significantly less use of steroids and ventilators." (PMID 37968660, 2023). "For example, NTproBNP and C-reactive protein plasma levels are more powerful prognostic predictors in heart failure patients." (PMID 37206106, 2023). "CRP, as the first known inflammatory biomarker to be elevated in patients with heart failure, was proposed in 1956." (PMID 36882679, 2023). "Elevated levels of TNF⍺, IL-6, CRP, Galectin-3, IL-2, IL-1β, IL-8, IL-33, and pentraxin-3 are all found in patients with heart failure." (PMID 36816471, 2023). "Two factors were associated with progression from prediabetes to DM: anthropometry and physical function (OR [95% CI]: 0.6 [0.5, 0.9], q = 0.04), and heart failure and c-reactive protein (OR [95% CI]: 1.4 [1.1, 1.7], q = 0.02)." (PMID 35850765, 2022). "Further, age, number of hospitalizations due to AE, hypercapnia, heart failure, OI, CRP, and D-dimer were also significant predictors of in-hospital mortality." (PMID 36104573, 2022). "Prognostic value of C-reactive protein (CRP) tertiles according to the heart failure (HF) categories." (PMID 36620625, 2022). "Previous studies have shown Ca-125, C-reactive protein, and uric acid to be potentially good prognostic markers in heart failure (HF)." (PMID 36014020, 2022). "With regard to CRP, a retrospective analysis of the Valsartan Heart-Failure Trial demonstrated that patients with high CRP levels had a higher risk of death or the first morbid event." (PMID 36185864, 2022). "Cox regression multivariate analyses showed that 30-day mortality, heart failure, hs-CRP, CK-MB, and the MELD-XI score upon admission were independent predictors." (PMID 35300593, 2022). "Baseline characteristics of the study population according to the heart failure (HF) categories and tertiles of C-reactive protein (CRP) levels." (PMID 36620625, 2022). "Due to the standard treatment of heart failure, CRP levels within each group were significantly lower on d21–d1 and d21–d3." (PMID 35407370, 2022). "The patient presented twice with concurrent cardiac insufficiency, hepatic and renal impairment, delirium with high C-reactive protein levels and the patient’s response to glucocorticoids, supporting the diagnosis of CRS." (PMID 36626467, 2022). "This was significantly influenced by the presence of comorbidities, hypotension, hypoxia, heart failure, acute respiratory distress, hypernatremia, abnormal liver profile, high C-reactive protein, and positive blood culture." (PMID 34059010, 2021). "IL-1 inhibition, with concomitant downstream IL-6 and CRP suppression, has been investigated most extensively in this domain of the literature and is an emerging target in heart failure management." (PMID 34571836, 2021).
heart failure (continued). "Incidence rates of heart failure/1000 person-years, missing values and numbers of men in each C-reactive protein and IL-6 quartile." (PMID 33709785, 2021). "The associations of CRP quartiles with MACE were mainly driven by higher rates of mortality and hospitalizations for heart failure." (PMID 34032303, 2021). "C-reactive protein: an inflammatory marker with prognostic value in patients with decompensated heart failure." (PMID 34817012, 2021). "Markers reported to be elevated were D-dimer, NT-proBNP, C-reactive protein, serum ferritin, procalcitonin, and IL-6, which implies involvement in circulatory disorders, cardiac insufficiency, and inflammatory reactions." (PMID 33807280, 2021). "Immunosuppression, history of heart failure, APACHE II and SAPS II scores, C-reactive protein and lactate at CRRT initiation were independently associated with mortality in multivariable Cox proportional hazards models." (PMID 33819306, 2021). "This study showed that age, certain comorbidities (cancer, heart failure, chronic renal failure), dyspnea, lower SpO2 and the laboratory parameters HCT, CRP, AST and Ferritin were independent risk factors associated with a fatal outcome." (PMID 33546639, 2021). "This study showed that age, certain comorbidities (cancer, heart failure, chronic renal failure), dyspnea, lower SpO2 and the laboratory parameters HCT, CRP, AST and Ferritin were potential risk factors associated with mortality." (PMID 33546639, 2021). "For the five outcomes of heart failure (HF), BMI, C-reactive protein (CRP) levels, HDL-cholesterol (HDL-C) and triacylglycerols, there was evidence for Co-localisation also protects at both GIP and GIPR." (PMID 34505161, 2021). "Heart failure-related parameter myoglobin, inflammatory parameters CRP and LDH were much higher in severe subgroup." (PMID 32695551, 2020). "CRP represents a composite heart failure biomarker, which is a robust predictor of cardiovascular and non-cardiovascular mortality." (PMID 33344515, 2020). "In our cohort, the results of NT-proBNP and CRP done during the RW admission, where heart failure was confirmed by the echocardiogram, were similar to the ones done in the ED." (PMID 32823938, 2020). "There were significant differences between age, baseline lactic acid, baseline C-reactive protein, baseline oxygen saturation, ventilator use, myocardial infection, heart failure, dementia, chronic pulmonary disease, and any malignancy." (PMID 33154452, 2020). "Our R2 value was 0.783, which means CRP and NT-proBNP had 78% ability to detect heart failure (p=0.001)." (PMID 32181077, 2020). "Patients with AF were significantly older; showed significantly higher C-reactive protein levels, more heart failure, chronic obstructive pulmonary disease and mortality." (PMID 31999778, 2020). "Laboratory investigations should include cardiac biomarkers such as nt-pro BNP for the assessment of heart failure, troponin I or T for myocyte necrosis and c-reactive protein (CRP) for inflammation." (PMID 31032264, 2019). "Other study has shown that the CRP level is significantly increased in patients with heart failure, and the increase degree is positively correlated with the severity and prognosis of heart failure." (PMID 31618407, 2019). "This suggests that TIIA can reduce the excessive CRP due to heart failure, thus exerting a protective effect on ventricular remodeling." (PMID 31618407, 2019). "Our results give an additional evidence of the inflammatory nature of severe heart failure in dogs as it was already documented with the use of CRP and cytokines in humans and dogs." (PMID 29573742, 2018). "CRP has been shown to elevated in more severe grades of heart failure and can independently predict morbidity and mortality in heart failure and TNF levels have been shown to do the same." (PMID 30453474, 2018).
heart failure (continued). "The present study is the first to report on serum CRP concentration in association with WBC and neutrophil count in patients with severe heart failure." (PMID 29573742, 2018). "Acute phase proteins as markers of inflammation, including CRP, have been found to be increased in acute and chronic inflammatory diseases and heart failure." (PMID 29573742, 2018). "Recently, two phase II studies utilised anakinra (a recombinant IL-1 receptor agonist) in patients following primary PCI and demonstrated reductions in CRP levels coupled with lower incidence of heart failure at 3 months." (PMID 30453474, 2018). "As well, although we analyzed the correlation between serum C-reactive protein (CRP), a classic biomarker for heart failure, and total cholesterol, another classic biomarker for cardiovascular disease, we did not detect a significant association." (PMID 28977908, 2017). "Other studies that evaluate the prognostic impact of high-sensitivity C-reactive protein according to the nutritional status should be conducted to better utilize inflammatory markers in heart failure patients." (PMID 27759823, 2016). "Frailty and heart failure would share a consistent correlation with some inflammatory biomarkers such as interleukin-6 and C-reactive protein." (PMID 27577747, 2016). "A CRP level >1.38 mg/dL indicates the strong possibility of a parapneumonic effusion, whereas a level <0.64 mg/dL indicates a heart failure pleural effusion." (PMID 27194820, 2016). "It was also shown that, CRP contributes to IL-6 expression which is a stronger prognostic predictor of heart failure than CRP." (PMID 25888309, 2015). "Urine NGAL levels and CRP was significantly higher in participants with heart failure compared to those with NT-proBNP below 400 pmol/l." (PMID 26070595, 2015). "Pacing-induced heart failure promotes systemic inflammation and was shown to have increased plasma CRP." (PMID 26265746, 2015). "After regarding PD-unrelated deaths (cancer deaths, vascular deaths, heart failure, and hepatic failure), as well as deaths from unknown causes, as censored due to “alternative outcomes,” the associations were very similar; the unadjusted and adjusted HR increased with log CRP concentrations." (PMID 26218286, 2015). "Although the serum concentrations of CRP are elevated in patients with heart failure, especially those with severe acute HF, clinical data regarding the prognostic value of CRP in patients with chronic heart failure have been sparse and inconsistent." (PMID 24885051, 2014). "There is evidence of elevated CRP levels in patients with heart failure in higher NYHA functional classes, with higher rates of hospital readmission and higher rates of mortality." (PMID 24244639, 2013). "Accumulating evidence suggests that an elevated C-reactive protein (CRP) level is an independent prognostic factor in patients with heart failure." (PMID 23372656, 2013). "In fact, it has been confirmed that the predictive cardiovascular value of ADMA is similar to that of B-type natriuretic peptide (a biomarker of heart failure) and C reactive protein (CRP, an inflammatory mediator)." (PMID 23109853, 2012). "We are not aware of any previous studies investigating the effects of temperature with BNP or with CRP in heart failure patients." (PMID 22588803, 2012). "In this study of 100 patients with heart failure and systolic dysfunction, we observed significantly higher BNP and CRP, which are biomarkers related to heart failure symptoms and prognosis, with 3- to 4-day moving averages of apparent temperature." (PMID 22588803, 2012). "One study found that CRP measurements (taken between 12 and 24 hours post event) predicted occurrence of heart failure (HR = 2.6, P = 0.04) and death (HR = 2.7, P = 0.02) post-MI." (PMID 20529285, 2010). "Patients with higher peak CRP levels were older, had more impaired kidney function and more often had a history of heart failure." (PMID 19583836, 2009).
heart failure (continued). "Patients with heart failure had lower hs-CRP levels (p < 0.001)." (PMID 40004724, 2025). "First, cachexia was assessed at discharge considering that heart failure patients experience increased C-reactive protein levels and an increase in body weight due to edema associated with congestion during acute exacerbations, which complicates the accurate assessment of cachexia at admission." (PMID 41510342, 2025). "The publication bias test was performed using the Begg test which shows that the P value of each outcome indicator was greater than 0.05 (heart failure markers: P = 0.061, CRP: P = 0.602, TNF-α: P = 0.317, and IL-6: P = 0.317), and therefore the possibility of publication bias was low." (PMID 41179565, 2025). "More than half of the patients withatherosclerotic cardiovascular disease are associated with systemic inflammation.The incidences of major adverse cardiovascular events (MACEs), heart failure(HF), and mortality increase significantly when the C-reactive protein (CRP)levels are ≥2 mg/L." (PMID 41209124, 2025). "Overall, higher levels of HbA1c associated with significantly higher incidence of all-cause mortality, irrespective of sex, LDL-C, CRP levels, smoking status, heart failure, and presence of acute coronary syndrome." (PMID 39985886, 2025). "A post-hoc, not prespecified analysis of the CORONA trial suggested that statin therapy may reduce CRP levels and decrease hospitalization rates among patients with heart failure." (PMID 40710370, 2025). "The groups differed from each other on several baseline parameters, including age, smoking, hemoglobin, albumin, CRP, creatinine, leukocytes, oxygen supply, peripheral oxygen saturation (pulse oximetry), body temperature, respiratory frequency, and prevalence of heart failure and COPD." (PMID 40271386, 2025). "All included studies: enrolled adult patients with acute or chronic heart failure, measured at least one inflammatory biomarker (IL-6, hs-CRP, or NLR), and reported multivariable-adjusted hazard ratios (HRs) for all-cause mortality and/or heart failure rehospitalization." (PMID 41375916, 2025). "This study aims to evaluate the impact of using a vHPSD catheter compared to an STD RF one, on variations in Brain Natriuretic Peptide (BNP), high‐sensitivity Troponin I (hsTnI), and C‐reactive protein (CRP) as biomarkers of heart failure, myocardial injury, and systemic inflammation, respectively." (PMID 40207269, 2025). "Furthermore, CRP levels correlate with adverse outcomes, including left ventricular dysfunction, heart failure, and mortality, making it a valuable prognostic tool." (PMID 40649166, 2025). "Notably, this study represents the first systematic identification of an inflection point and quantitative characterization of the threshold effect in the hs-CRP-heart failure relationship among Chinese adults." (PMID 40998984, 2025). "Patients with heart failure often have an inflammatory response, and inflammatory markers such as high-sensitivity C-reactive protein (hs-CRP), interleukin-1β (IL-1β), and interleukin-6 (IL-6) play important roles in the occurrence and development of heart failure." (PMID 41333015, 2025). "Moreover, CRP and UA are both potentially good prognostic markers in heart failure and can also be used as adjunctive parameters in the early diagnosis and follow-up of right cardiac disorders." (PMID 41614870, 2025). "Although many of the patients suffered from other conditions (e.g., cardiovascular disease, heart failure, inflammatory diseases in other organs), which can contribute to the elevated CRP levels, the degree of increase is less pronounced than in the case of bacterial purulent bronchopneumonia." (PMID 40943857, 2025). "For example, only TnT (biomarkers of damage to heart muscle) and NT-proBNP (bio-marker of heart failure) showed continuous increase post-treatment in sarcoma patients versus CRP (biomarker for inflammation) and TNFα (biomarker for heart failure) in breast cancer patients." (PMID 40014780, 2025).
heart failure (continued). "And speculated that high cholesterol levels and higher CRP level can improve myocardial energy level and ability to resist infection in patients with heart failure, thus improved the prognosis of patients." (PMID 39099668, 2024). "Moreover, they observed that hs-CRP increased prior to the occurrence of heart failure or death, supporting the role of inflammation in the clinical deterioration of patients with CHD." (PMID 38673472, 2024). "Asymptomatic heart failure patients with elevated creatinine level and CRP levelreceived cardiovascular magnetic resonance imaging and the results demonstrated alesion in the cardiac (late gadolinium enhancement in the middle segment ofinter-ventricular septum in short-axis view)." (PMID 39076541, 2024). "Likely differentials were narrowed down to hepatic dysfunction from AOSD flare (recent change in immunosuppressive regimen, elevated CRP, and ferritin) or congestive hepatopathy from heart failure (clinical presentation of heart failure and depressed left ventricular function on echocardiogram)." (PMID 38883113, 2024). "Furthermore, having heart failure, low SBP, low oxygen saturation, elevated respiratory rate, high CRP and blood glucose levels on admission were associated with poor prognosis." (PMID 39036024, 2024). "Also, beneficial effects were obtained on CRP, a marker of inflammation, and NT-proBNP, a marker of cardiac insufficiency." (PMID 38627784, 2024). "Furthermore, having heart failure, low systolic blood pressure (SBP), low oxygen saturation, elevated respiratory rate, high CRP and blood glucose levels on admission were associated with poor prognosis." (PMID 39036024, 2024). "Other significant factors included NT-proBNP (Rank 3, Mean = 4.4, SD = 1.7, Correlation = −0.03) and highly sensitive C-reactive protein (hsCRP; Rank 5, Mean = 5.9, SD = 2.3, Correlation = 0.004), which are often used for biomarkers related to heart failure and inflammation, respectively." (PMID 39797104, 2024). "Another key aspect concerns inflammation, frequently measured by high-sensitive C reactive protein (hs-CRP) or the neutrophil-to-lymphocyte ratio (NLR), which is known to be linked to the risk of developing cardiovascular disease, such as heart failure and atrial fibrillation." (PMID 38893039, 2024). "Additionally, C-reactive protein (CRP) serves as a general indicator of body-wide inflammation which can exacerbate heart failure." (PMID 37537380, 2024). "Furthermore, serial CRP measurements seem to provide prognosis after hospital discharge, identifying CHD patients at higher risk of re-admission for heart failure." (PMID 38673472, 2024). "Significant reduction of hs-CRP and improvement of heart failure outcomes in the IL1-ra group." (PMID 39124834, 2024). "The final multivariable model including S. aureus as an etiologic agent, worsening of heart failure, and CRP at diagnosis adjusted for age and sex showed optimal discrimination with a C statistic of 0.840 (95% CI 0.725–0.955) and demonstrated good calibration with a Hosmer–Lemeshow p value of 0.231." (PMID 39330882, 2024). "Therefore, in the Heart and Soul study, the follow-up of patients with established CHD indicated that heart failure incidence emerges to be relatively elucidated by abnormal diastolic function in patients with high CRP levels." (PMID 36882679, 2023). "The potentialcausality between HDL and heart failure, the role of HDL in the pathogenesis ofHF, and its interaction with C-reactive protein (CRP), triglycerides(TG), and monocytes in the process of heart failure have been briefly summarizedand discussed in this article." (PMID 39076447, 2023). "In circulatory disorders, elevated CRP levels in patients with coronary syndromes, which may progress to heart failure, are strongly correlated with dense plaque composition." (PMID 38035097, 2023).